CXCR4 (C-X-C motif chemokine receptor 4)
Diseases named in the same sentence as CXCR4 in open-access papers (continued):
Sharing a sentence is not in itself a finding about the gene and the disease.
cervical carcinoma (continued). "A new cytokine (CXCL16) was investigated together with the chemokine receptor combination CXCL12/CXCR4 and CXCL16/CXCR6 in cervical intraepithelial neoplasia (CIN) and cervical cancer." (PMID 34833360, 2021). "Inhibition of CXCR4 expression and function significantly impairs the growth potential of the HTB-35 cervical carcinoma cell line in vivo and efficiently decreases the lung and spleen metastasis in an animal NOD-SCID model." (PMID 24728301, 2014). "In cervical cancer, CAFs and B cells communicate through MIF-(CD74+CXCR4) and MIF-(CD74+CD44)." (PMID 38157264, 2023). "The authors found that CXCR4 was expressed on SCC cells in all cervical cancer tissues, metastatic lymph node, and Hela cells, but not in normal cervical tissue." (PMID 34833360, 2021). "Studies on human cervical carcinoma (HCC) demonstrated high expression of CXCR4 in HCC-derived cell lines and in tissue sections, while normal cervical epithelium was negative." (PMID 20049170, 2010). "Although there are currently no studies demonstrating the role of 68Ga-Pentixafor in cervical cancer, it appears that CXCR4-targeted imaging could potentially be used to prognosticate patients as well as to select patients who may benefit from therapies targeting CXCR4." (PMID 36140541, 2022). "Blood-born metastasis of cervical cancer are not uncommon especially in third world countries, prompting us to investigate the relationship between the SDF-1α/CXCR4 axis, the HPV-16/18-E6/E7 genes, and tumor metastasis." (PMID 19325708, 2009). "In addition, the suppression of CXCR7 can inhibit the progression of cervical cancer cells induced by CXCL12, but CXCR4 is not involved in these processes." (PMID 35264069, 2022).
diabetes (48 papers, 2008 to 2025). "Indicative of a dysfunctional signaling environment in situ, the expression of multiple growth factors and cytokines (Vegf-a, Fgf-2, Pdfg-a, and Sdf-1; P <0.02) as well their associated receptors (Cxcr-4, Fgfr-2, and Pdgfr-a; P <0.01) was significantly decreased in the setting of diabetes." (PMID 24943716, 2014). "In previous studies, CXCR4+ T cells recruited by SDF-1α prevented the development of T1D in an adoptive cell transfer of diabetes." (PMID 38490439, 2024). "The chemokine signaling mediated by CXCR4 plays a key role in modulating the activity of myeloid-derived suppressor cells that had function in regulating insulin tolerance in diabetes." (PMID 38221932, 2024). "Circulating ASC level was analyzed before and 8 h after therapy with the CXCR4 antagonist plerixafor in two patients with diabetes: a man aged 68 with a BMI of 25.3 kg/m2 and a woman aged 69 with BMI of 33.6 kg/m2." (PMID 36952215, 2023). "Under endocrine disorder ‘experimentally induced diabetes’ was linked to Harvey Rat Sarcoma Viral Oncogene Homolog (H-RAS), C-X-C motif chemokine receptor 4 (CXCR4) and transforming growth factor-beta 1 (TGF-β1)." (PMID 36934129, 2023). "Disruption of SDF-1–CXCR4 binding by the CXCR4 antagonist AMD3100 accelerates the development of diabetes in adoptive transfer models and induces beta-cell apoptosis." (PMID 37400916, 2023). "Our previous study revealed that the CXCR4 was enhanced only in the DRG neurons at week 2 (early phase of diabetes) after STZ injection." (PMID 35799894, 2022). "Although the role of CXCL12 in diabetes is complex, the CXCL12/CXCR4 axis in adipose tissue has been associated with the production of proinflammatory cytokines and, finally, systemic insulin resistance." (PMID 35740314, 2022). "We document the interaction between infarct and diabetes on the migratory activity of CD34+/CXCR4+ cells." (PMID 36465463, 2022). "When controlling for duration of diabetes between the high and undetectable residual beta-cell groups, group*time interactions remained for CXCR4+ HPCs (p=0.014), CXCR7+ HPCs (p=0.030) and CXCR7+ EPCs (p=0.007), but not for HPCs (p=0.060)." (PMID 35222269, 2022). "Together, this work demonstrates the clinical potential of small molecule CXCR4 agonists as novel therapies for pathologic wound healing in diabetes." (PMID 35216311, 2022). "Reducing CXCR4-mediated nociceptor hyperexcitability can reverse pDN in HFD mice, suggesting that CXCR4 in Nav1.8 positive DRG neurons is involved in the development of mechanical allodynia in HFD-induced diabetes." (PMID 35795572, 2022). "In patients with diabetes, the association was the opposite, with a 55% reduction in the proportion of migrated CD34+/CXCR4+ cells." (PMID 36465463, 2022). "Genes co-expressed with PTPN6 were correlated with “Immune response_T cell co-signaling receptors, schema”, “Breakdown of CD4+ T cell peripheral tolerance in type 1 diabetes mellitus”, and “Chemotaxis_SDF-1/CXCR4-induced chemotaxis of immune cells”." (PMID 36556168, 2022). "Despite this, we showed that the increased circulating HPCs and EPCs from pre- to post-exercise in the type 1 diabetes group, CD34+ HPCs, CD34+VEGFR2+, CD34+VEGFR2+CXCR4+ EPC counts were significantly attenuated compared to the non-diabetes controls." (PMID 34267242, 2021). "In other disease models, chemokines are involved in the fibrosis process of injured tissues, much like CCL5 contributes to liver fibrosis in non-alcoholic fatty liver disease progression and CXCR4 contributes to cardiac fibrosis in diabetes." (PMID 31164836, 2019). "The binding of TLR4 and CXCR4 to HMGB1 is crucial to trigger chronic inflammation response in diabetes." (PMID 30647535, 2018). "EPC from patients with CAD or diabetes have been shown to be functionally impaired, and the CXCR4 importantly modulates the migratory and angiogenic capacities of human EPC." (PMID 27200368, 2016).
diabetes (continued). "Taken together, the current data demonstrate that the CXCR4 pathway plays a role in the pathogenesis of cardiac in experimental diabetes." (PMID 26214690, 2015). "CXCR4 antagonism markedly reduced cardiac fibrosis in both models of diabetes, similar in magnitude to that seen with candesartan." (PMID 26214690, 2015). "Taken together the current data indicate that pharmacological inhibition of CXCR4 significantly reduces diabetes induced cardiac fibrosis, providing a potentially important therapeutic approach." (PMID 26214690, 2015). "Further studies of the potential therapeutic utility of CXCR4 antagonism in mitigating or possibly reversing the longer term cardiovascular and renal complications of diabetes should be considered." (PMID 26214690, 2015). "Regarding the subpopulation of CD45dimCD34+KDR+ cells also expressing the homing marker CXCR4+, all diabetes treatment categories presented significantly decreased circulating levels by comparison with nondiabetic patients." (PMID 24934236, 2014). "Our data suggest that Ad-CXCR4 primed EPCs have better therapeutic effects for ischemia stroke in diabetes than unmodified EPCs do." (PMID 23185548, 2012). "This study investigated the role of stromal cell-derived factor-1α (SDF-1α)/CXC chemokine receptor 4 (CXCR4) axis in brain and endothelial progenitor cells (EPCs), and explored the efficacy of CXCR4 primed EPCs in treating ischemic stroke in diabetes." (PMID 23185548, 2012). "Meanwhile, a persistent increase in CXCR4 and high blood glucose may further exacerbate astrocyte dysfunction at the late phase of diabetes." (PMID 35799894, 2022). "Moreover, pharmacologic antagonism of CXCR4 with candesartan was shown to reduce diabetes-induced cardiac fibrosis." (PMID 35048778, 2022). "Therefore, we specifically assessed the spinal cord dorsal horn CXCR4 variations in rats at the early and late phases of diabetes." (PMID 35799894, 2022). "Both CXCR4 and CX43, which are localized and coexpressed in neurons and astrocytes, were enhanced significantly in the dorsal horn of spinal cord in rats undergoing DNP during late phase of diabetes, and the CXCR4 antagonist AMD3100 reduced the expression of CX43." (PMID 35799894, 2022). "It is speculated that elevation in the expression of proinflammatory CXCR4 occurred in rats with DNP at the late phase of diabetes, and it subsequently induced increases in CX43 expression." (PMID 35799894, 2022). "As exercise mobilised HPCs and EPCs negative for CXCR4 and CXCR7 in the controls, but not the type 1 diabetes group, this suggests pathways other than stromal cell–derived factor-1α (SDF-1α)/CXCR4 are also impaired by deregulated glucose control seen in diabetes." (PMID 34267242, 2021). "CXCR4 expression was significantly reduced on EPCs from patients with diabetes or on EPCs treated by high glucose, which could contribute to dysfunctional EPCs in diabetes." (PMID 31964421, 2020). "HIF-1α is associated with retinal inflammation induced by diabetes, Egr-1 may play a role in the development of vascular complications of DM, and the CXCL12/CXCR4 chemokine axis contributes to neovascularization." (PMID 32722545, 2020). "The presence of diabetes in rats or intravitreal injection of HMGB1 in normal rats significantly upregulates the levels of mRNAs encoding SDF-1/CXCL12 receptor CXCR4, as well as levels of HIF-1, EGR-1, TK-2, and CXCL12/CXCR4 proteins in the chemokine axis." (PMID 30473885, 2018). "The presence of CXCR4 expressing immune cells with the prevalence of CD3 positive T-cells in diabetic DRG may have important implications for the generation of pain in diabetes." (PMID 24961298, 2014). "Simultaneously, CXCR4/SDF-1 signaling may coordinate inflammation in diabetic DRG that could contribute to the development of pain in diabetes." (PMID 24961298, 2014). "CXCR4/SDF-1 signaling may simultaneously coordinate inflammation in diabetic DRG that could contribute to the development of pain in diabetes." (PMID 24961298, 2014).
diabetes (continued). "In summary, the present study demonstrates that transfusion of Ad-CXCR4 primed EPCs may be a novel approach for enhancing therapeutic benefits for ischemic stroke in diabetes." (PMID 23185548, 2012). "CXCR4 antagonists could reduce diabetes‐induced cardiac fibrosis." (PMID 38617433, 2024). "CXCL12/CXCR4 and CCR4 were also found to be one of the targets for the treatment of diabetic neuropathic pain." (PMID 38617433, 2024). "The decrease in the CXCR4 expression by GLC treatment as confirmed by Western blot and Immunohistochemistry suggests an anti-inflammatory effect in the diabetic cardiac atrophy." (PMID 33924458, 2021). "By contrast, DNP induces upregulation of TNF-α and CXCR4 in the DRG at both the early phase and the late phase of diabetes." (PMID 31001066, 2019). "Both TLR4 and CXCR4 are G protein-coupled receptors and can bind to the HMGB1 in cytoplasm, which expression level is elevated in diabetes." (PMID 30647535, 2018). "Treatment of NOD mice with CXCR4 antagonist AMD3100 mobilizes T cells from the bone marrow to peripheral lymphoid tissues, and significantly delays the onset of insulitis and diabetes." (PMID 18793419, 2008). "Treatment of NOD mice with AMD3100, an antagonist for CXCL12's receptor CXCR4, mobilizes T cells and HSC from the bone marrow to the periphery, concomitantly inhibits insulitis and delays the onset of diabetes." (PMID 18793419, 2008). "As a previous study demonstrated, in STZ-induced diabetic rats, the proinflammation proteins TNF-α and CXCR4 were both enhanced at the initial phase (2 weeks) of diabetes in the DRG but did not change in the spinal cord dorsal horn." (PMID 35799894, 2022). "The protein levels of the proinflammatory CXCR4 in the spinal cord was significantly increased at week 5 (late phase), but not at week 2 (early phase) of diabetes, which is in line with our previous report." (PMID 35799894, 2022). "Additionally, circulating number of all HPCs and EPCs expressing CXCR4 and CXCR7 were significantly lower in the type 1 diabetes group than the matched non-diabetes controls." (PMID 34267242, 2021). "The protein expressions of both CXCR4 and TNF-α were significantly increased early at 2 weeks of diabetes as compared to the control, and the DRG TNF-α and CXCR4 protein expression maintained significantly increased by 5 weeks of diabetes (P < 0.05, diabetes vs. control)." (PMID 31001066, 2019). "Addition of either of the CXCR4 inhibitors (30 mg/kg for POL5551 and 10 mg/kg for Plerixafor) after the ninth G-CSF dose could rescue diabetes-induced hyporesponsiveness to G-CSF." (PMID 24072044, 2013). "One potential issue is that the diverse comorbidities of diabetes (e.g. ocular, cutaneous, neurological, cardiovascular, and muscular conditions) and their inherent genetic components likely result in a different finding concerning the impact of SDF-1/CXCR4 gene variations with DKD." (PMID 39512693, 2024). "Resting counts were highest for participants without diabetes, lower for Cpephigh group (CXCR4+ and CXCR7+ HPCs significantly so) and lowest in those with undetectable C-Peptide (all phenotypes significantly lower than controls, CXCR7+ EPCs significantly lower than Cpephigh)." (PMID 35222269, 2022). "Comparatively, NAC given via daily oral administration to rats with DNP maintained the behavioral responses as evaluated by PWT and PWL at a level that was comparable to that seen in the nondiabetic control rats and downregulated CXCR4 in the late phase of diabetes." (PMID 35799894, 2022). "All these results suggested that activated CX43 and CXCR4 could affect the development of DNP in STZ-induced type 1 diabetic rats via dysfunctional astrocytes and activated neurons in the spinal cord dorsal horn at the late phase of diabetes." (PMID 35799894, 2022).
diabetes (continued). "Furthermore, CXCR4 protein was enhanced in both the DRG and the spinal cord dorsal horn at week 5 (late phase of diabetes), which was consistent with the upregulation of proinflammatory protein expression in other neuropathic pain models (e.g., cancer pain model, nerve ligation)." (PMID 35799894, 2022). "This study aimed to investigate transcript levels of Metastasis-associated lung adenocarcinoma transcript 1 (MALAT1), microRNA (miR)-1-3p, and C-X-C motif chemokine receptor 4 (CXCR4) in the DN patients and type 2 diabetes mellitus (T2DM) cases without neuropathy." (PMID 35368523, 2022). "For EPCs and CXCR4+ EPCs no significant group*time existed (p>0.053), however the Cpepund group had significantly lower group counts compared to both the non-diabetes controls and Cpephigh groups for these phenotypes (p<0.013)." (PMID 35222269, 2022). "To look into the mechanism that might be attributable to the reduced thresholds of mechanical allodynia and heat hyperalgesia during the earlier phase of diabetes, we further investigated the status of TNF-α and CXCR4 protein expression over time in the DRG in addition to that in the spinal cord." (PMID 31001066, 2019). "Both the spinal cord TNF-α and CXCR4 protein expressions were significantly increased at 5 weeks (P < 0.05) but not at 2 weeks of diabetes (P > 0.05, diabetes vs. control) despite significant reductions in the thresholds of PWT and PWL as early as 1 week of diabetes as compared to control." (PMID 31001066, 2019). "While at the late phase of diabetes (i.e., 5 weeks), the protein expression of both CXCR4 and TNF-α all significantly increased in the spinal cord and in the DRG, which corresponds to a significant reduction of the paw withdrawal threshold and latency at 5 weeks of diabetes." (PMID 31001066, 2019). "The percentage of CXCR4 expressing MNC and lymphocytes in the BM were both negatively associated with disease severity (rho = −0.255, P = 0.015 and rho = −0.245, P = 0.020), but not with diabetes." (PMID 23383236, 2013). "The percentage of CXCR4 and CD26 expressing MNC and lymphocytes in the circulation was not influenced by severity of CLI or presence of diabetes." (PMID 23383236, 2013). "By contrast, CXCR4 and TNF-α in the spinal cord dorsal horn did not significantly increase at 2 weeks of diabetes while both were significantly upregulated at 5 weeks of diabetes." (PMID 31001066, 2019). "Whilst the induction of diabetes did not increase the overall myocardial burden of GFP+ cells, it was accompanied by an increase in GFP+ cells expressing the fibroblast marker alpha-smooth muscle actin and this was attenuated by CXCR4 antagonism." (PMID 26214690, 2015). "The proportion of CD34+/CXCR4+ cells within blood mononuclear cells was 1.96 times higher after STEMI compared with NSTEMI (GMR = 1.96, 95% CI 0.87, 4.37) and 1.55 times higher in patients with diabetes compared to patients without diabetes (GMR = 1.55, 95% CI 0.77, 3.13)." (PMID 36465463, 2022).